HSPA6 (heat shock protein family A (Hsp70) member 6)
Diseases named in the same sentence as HSPA6 in open-access papers (continued):
Sharing a sentence is not in itself a finding about the gene and the disease.
HSPA6 also shares sentences with these, for which no sentence is quoted: leukemia (3 papers); colorectal cancer (2); esophageal cancer (2); osteosarcoma (2); acute myeloid leukemia (1); amyotrophic lateral sclerosis (1); chronic hepatitis (1); Cirrhosis (1); endometrial cancer (1); esophageal squamous cell carcinoma (1); kidney cancer (1); liver cancer (1); lymphoma (1); multinodular goiter (1); nephritis (1); Oral squamous cell carcinoma (1); ovarian carcinoma (1); ovarian clear cell adenocarcinoma (1); Parkinson disease (1); renal carcinoma (1); Respiratory Syncytial Virus Infection (1); rheumatoid arthritis (1); serous ovarian carcinoma (1); SeSAME syndrome (1); Tetralogy of Fallot (1); uterine corpus endometrial carcinoma (1); viral infection (1).